BDNF (brain derived neurotrophic factor)
Diseases named in the same sentence as BDNF in open-access papers (continued):
Sharing a sentence is not in itself a finding about the gene and the disease.
Stroke (continued). "The diminished level of BDNF led to more severe stroke pathophysiology with reduced angiogenesis and intraventricular injection of BDNF induced neurogenesis in the animal model, implying their roles in neurogenesis and neuronal cell protection during stroke." (PMID 35887140, 2022). "The experimental results showed that, compared with the direct injection of BDNF, the diffusion time of hydrogel-delivered BDNF from the stroke cavity to the surrounding infarct tissue was prolonged, and the recovery of motor function was promoted." (PMID 35458307, 2022). "Although we have investigated the temporal profile of MMP-9 and BDNF concentrations, we emphasize that our results require confirmation in larger sample size and different stroke subtype populations." (PMID 36092813, 2022). "We found that r-hGH treatment after stroke resulted in a significant global increase of 25-35% in pro-BDNF expression in the investigated regions." (PMID 35465399, 2022). "Currently, researches on mental and neurological disease (e.g., stroke, mood disorders, and neurodegenerative diseases) found that abnormal BDNF signaling is involved in the diseases." (PMID 35814950, 2022). "Three trials described the change in the serum BDNF concentrations in post-stroke individuals participating in regular EA, with a duration ranging from 8 to 12 weeks." (PMID 35743624, 2022). "Of note, only one systematic review has directly assessed the effects of PA and post-stroke BDNF concentration." (PMID 35743624, 2022). "In contrast, other studies have found increased serum BDNF levels in individuals with stroke following rehabilitative programs." (PMID 36556107, 2022). "In animal models, post-stroke delivery of brain-derived neurotrophic factor (BDNF) has given promising effects." (PMID 35756121, 2022). "In the stroke patients, the levels of BDNF ranged from 1.43 to 29.61 ng/mL, and in the healthy controls, the range was 5.23–35.06 ng/mL." (PMID 35756121, 2022). "A significant reduction was also noted when serum BDNF levels were compared between week one and week three of acute inpatient stroke rehabilitation." (PMID 36556107, 2022). "Recently, a number of clinical studies have reported the advantageous impact of various types of endurance activity (EA) on enhancing BDNF levels in the peripheral blood in post-stroke patients." (PMID 35743624, 2022). "BDNF also has shown to modulate the effects of tDCS during chronic stroke-induced aphasia treatment and have a key role in mediating the beneficial effects of tDCS on explicit memory." (PMID 35330487, 2022). "Our study confirms that stroke significantly decreases the level of BDNF in various domains such as cognition, affect, and motor function." (PMID 35287688, 2022). "Increased BDNF expression and mature BDNF protein were also observed in task-trained stroke mice treated with the DNMT inhibitor 5-aza-dC." (PMID 36142283, 2022). "In conclusion, stroke significantly affects the level of BDNF, which is positively correlated with neural plasticity and post-stroke recovery in various domains such as cognition, affect, and motor function." (PMID 35287688, 2022). "Treadmill high-intensity interval training for 20 min a day elicited significantly greater acute increases the level of BDNF in the serum of post-stroke patients and corticospinal excitability." (PMID 36142421, 2022). "Accordingly, instead of circulating levels of BDNF in the first days after stroke, the sustaining reduction of peripheral BDNF expression at the acute stage is likely to correlate with poor clinical outcomes in patients with AIS." (PMID 36092813, 2022). "Among stroke survivors, a mean blood lactate concentration of >4.7 mmol/L after 20 min of exercise was sufficient to promote a significant increase in BDNF concentration." (PMID 35743624, 2022).
Stroke (continued). "Astrocytes also produce multiple growth factors such as VEGF, IGF-1, and BDNF, and decreased expression of these growth factors is a feature of aging astrocytes and a possible explanatory factor for the typically severe stroke outcomes seen in older animals." (PMID 34570349, 2022). "Among many factors believed to attribute to this process, Brain-derived Neurotrophic Factor (BDNF) is a neurotrophin coordinating neuroplasticity after various neurological disorders such as stroke." (PMID 35287688, 2022). "The close relationship between BDNF SNPs and the post-stroke outcome has been delineated in post-stroke motor recovery." (PMID 35330487, 2022). "Increased expression of BDNF has been observed in subacute and chronic stroke patients with neuropathic pain, suggesting that BDNF is involved in pain recovery after stroke." (PMID 36683849, 2022). "Brain-derived neurotrophic factor (BDNF), recognized as a nerve growth factor and released from MSCs, has been widely researched in different brain diseases, including stroke, neurodegenerative diseases, and others." (PMID 35769327, 2022). "The expression of BDNF was found to be triggered by brain injury as part of the neuroprotective response following a stroke." (PMID 35814950, 2022). "r-hGH increases pro-BDNF within the peri-infarct area and regions that are known to experience secondary neurodegeneration after stroke." (PMID 35465399, 2022). "The plasma BDNF levels in the stroke patients (6.69 ± 4.92 ng/mL; mean ± SD) were significantly lower than in the age and gender matched control group (16.70 ± 7.20 ng/mL; mean ± SD; p < 0,0001; Mann-Whitney U test, GraphPad Prism)." (PMID 35756121, 2022). "In a rat model of stroke, niacin treatment significantly not only increased the brain-derived neurotrophic factor (BDNF), but also synaptic plasticity and axonal growth." (PMID 36584228, 2022). "There is an urgent need to focus on comorbid conditions in post-stroke patients and their relationship with the BDNF levels." (PMID 35743624, 2022). "In particular, the phosphorylation of CREB following activation of the PI3K/Akt pathway induces post-stroke restoration through the upregulation of neurogenic agents, such as nerve growth factor and brain-derived neurotrophic factor." (PMID 35405992, 2022). "In females, the BDNF levels were 61% lower in the stroke patients than in the healthy controls, and in males the BDNF levels were 57% lower in the stroke patients than in the healthy controls." (PMID 35756121, 2022). "Some studies have suggested that irisin can upregulate the level of brain-derived neurotrophic factor (BDNF), which can protect nerve cells from damage during stroke." (PMID 36135450, 2022). "This is probably because it was a pioneering article in the field of endurance exercise, cognitive function, and peripheral BDNF expression in post-stroke individuals and because it was published four years before the second-oldest study." (PMID 35743624, 2022). "One recent meta-analysis study has reported a correlation of BDNF levels with acute stroke; it was concluded that the level of serum BDNF is significantly lower in stroke patients compared to controls." (PMID 35625880, 2022). "Five trials assessed the change in the serum BDNF concentration immediately after a single bout of EA in post-stroke individuals." (PMID 35743624, 2022). "The neuroprotective role of BDNF in stroke has been demonstrated in subsequent intervention studies using exogenous BDNF." (PMID 35177977, 2022). "The difference slightly increased with age: In the youngest age group (<67 years of age) BDNF levels in stroke patients were 45.6% of the levels measured in the healthy controls." (PMID 35756121, 2022). "More large-sample clinical trials exploring the alteration of serum BDNF levels in PSD among stroke patients need to be conducted to verify this result." (PMID 35664480, 2022).
Stroke (continued). "An alternative method is to carry BDNF with a depot that was previously injected into the stroke cavity and release BDNF into the adjacent surrounding area." (PMID 36547301, 2022). "A recent study demonstrated that during cerebral ischemia-reperfusion, irisin regulates BDNF expression in the rodent stroke model, which indicates that irisin confers its beneficial effect through BDNF in ischemic stroke." (PMID 35164383, 2022). "What is the specific mechanism of BDNF production, neuroprotective effect, and regulation of glial cell function in acute brain injury (e.g., stroke or brain trauma) and its recovery period?" (PMID 35814950, 2022). "This implies that stroke can lead to an irreversible decrease in the level of BDNF or the rate of neural recovery." (PMID 35287688, 2022). "When BDNF was attached to the OX26 antibody using the biotin-streptavidin conjugation method for the treatment of stroke, it was seen that there was a nearly 243 percent increase in motor activity compared to BDNF delivered alone." (PMID 36559214, 2022). "Clinical trials on endurance exercise and post-stroke BDNF concentration and their quality evaluation based on the Web of Science Core Collection (Clarivate Analytics)." (PMID 35743624, 2022). "With this study, we confirm that the BDNF level is significantly lower in the patients with stroke than in the healthy controls." (PMID 35287688, 2022). "Platelets appear to play a complex, dual role in stroke etiology, however, also reducing hemorrhagic transformation and enhancing delayed repair, possibly by the direct release of stored BDNF." (PMID 35309561, 2022). "As BDNF is the major representative of neuroplasticity within nervous system, it is believed that stroke has a significant impact on the CNS regeneration, which is permanent if left untreated." (PMID 35287688, 2022). "Di Lazzaro previously reported the stability of serum BDNF during the acute stroke phase in ten patients with first-ever acute ischemic stroke." (PMID 33809965, 2021). "The data suggest that R1 promotes the recovery of neurological function after stroke via the BDNF/Akt/CREB signaling pathway." (PMID 34025400, 2021). "In another study, it was shown that AT improves functional recovery in stroke patients by increasing the BDNF level." (PMID 35096297, 2021). "Both clinical and animal experiments show that HIIT can evoke higher levels of brain-derived neurotrophic factor (BDNF) production to improve the brain function in health, diabetics, and stroke patients." (PMID 33716776, 2021). "Its low concentration in blood in the acute phase of IS is considered a negative prognosis factor; on the contrary, physical exercise can increase local levels of BDNF in the brain, leading to improvement in stroke recovery." (PMID 34571720, 2021). "From the literature search performed, only three studies yielded the investigation of the correlation between language impairment or aphasia in stroke and BDNF genotypes, highly suggesting that knowledge in this topic of interest is relatively new and limited." (PMID 34367374, 2021). "The authors reported that BDNF levels measured during the acute stroke phase in patients with poor outcome (mRS = 3–6) were lower compared to those with good outcome (p < 0.001) and that BDNF was an independent stroke outcome predictor." (PMID 33809965, 2021). "An integrative review has reported lower BDNF levels in patients with stroke; in one data-driven study, stroke patients with low levels of serum BDNF had significantly higher prevalence of cognitive dysfunction than healthy controls." (PMID 33671531, 2021). "Although, in regression analysis, BDNF levels were not correlated with the functional outcome on short-term follow-up, at 2 and 7 years after, low levels of BDNF at the acute stroke phase were correlated with poor functional outcome (mRS = 3–6)." (PMID 33809965, 2021).
Stroke (continued). "In acute stroke, low BDNF levels have been correlated with worse scores in the National Institute of Health stroke scale (NIHSS), larger infarct volume, and poor long-term functional outcome." (PMID 33809965, 2021). "Brain-derived neurotrophic factor (BDNF), one subtype of neurotrophin (nerve growth factors), has drawn extensive attention from stroke researchers." (PMID 34141514, 2021). "Expression of the neurotrophin BDNF has been shown to be upregulated in particular in the border zone (penumbra) of the infarct indicating a potential role in post-stroke recovery." (PMID 34572573, 2021). "Activated reactive astrocytes protect neurons after stroke by producing a variety of neurotrophic factors, including nerve growth factor, basic fibroblast growth factor, BDNF, and glial cell–derived neurotrophic factor." (PMID 34234667, 2021). "It has been reported that AMPA receptor-induced local BDNF signaling mediates motor neuron recovery in a mouse model of focal stroke." (PMID 34572573, 2021). "The authors reported a significant increase in BDNF concentration measured at day four post-stroke in the saffron-treated group compared to the control." (PMID 33809965, 2021). "Notch pathway was involved in AST induced differentiation of NSCs, NGF, IL-7, and BDNF-TrkB pathway took part in proliferation and the neuronal differentiation of NSCs after stroke in vivo." (PMID 33716673, 2021). "The serum BDNF levels were found to be negatively correlated with scores on the NIH Stroke Scale (NIHSS) (r = - .286, p < .001), so lower serum BDNF levels were associated with increasing severity of stroke." (PMID 34141514, 2021). "MacLellan has also reported a positive correlation between BDNF and post-stroke rehabilitation in stroke models." (PMID 33809965, 2021). "In patients with unfavorable outcome, a gradual decrease in BDNF levels in PBMCs before thrombolysis to the third day after stroke was reported (−64%, p = 0.013)." (PMID 33809965, 2021). "We conducted this systematic review and meta-analysis, aiming to study the role of BDNF as a biomarker in predicting the functional outcome of stroke when measured in the acute stroke phase." (PMID 33809965, 2021). "Although candidate mediators (i.e., serum TMAO, IL-17, IL-10, and BDNF) were comparable in the acute phase of stroke, there were differences in biological functions such as the membrane transport and amino acid metabolism between the two groups." (PMID 35153980, 2021). "Mice isolated immediately after stroke have shown brain tissue with decreased levels of brain-derived neurotrophic factor (BDNF), a molecule that aids in synaptogenesis and the growth, repair, and maturation of neuronal cells." (PMID 34299756, 2021). "The objective of this cross-sectional study was to measure plasma NRG-1 in children with SCA and determine if NRG-1 levels are correlated with severity of hemolysis or known biomarkers of stroke risk in SCA, PDGF-AA and BDNF." (PMID 35935682, 2021). "Nonetheless, both stroke severity, the timing of BDNF measurement after stroke, and all the other study characteristics reported were comparable among the studies we included." (PMID 33809965, 2021). "Clinical results discussing the relationship between BDNF and miRNAs in stroke in humans are very limited." (PMID 32944919, 2021). "In this study, an increase in the expression of p-CREB, p-Akt and BDNF was identified after the daidzein treatment, which demonstrated that the BDNF/Akt/CREB signaling channel had a considerable impact on functional recovery after stroke." (PMID 35095491, 2021). "One genetic variation of interest is the Val66Met single-nucleotide polymorphism of the brain-derived neurotrophic factor (BDNF) gene in humans, a potential clinically significant genetic variation associated with stroke risk and prognosis." (PMID 34367374, 2021).
Stroke (continued). "Our results suggested that music therapy promotes BDNF accumulation and influences neuron repairing and synapse regeneration, whereas noise has an adverse effect on brain repair after stroke." (PMID 34262520, 2021). "A total of seven studies measured serum BDNF and evaluated the differences between stroke patients (six studies included only ischemic stroke patients and one both ischemic and hemorrhagic) and healthy controls." (PMID 33809965, 2021). "The correlation between low serum BDNF levels in the first day after stroke and the poorer long-term functional prognosis is well documented." (PMID 33920472, 2021). "A randomised controlled trial (RCT) in Taiwan compared the effect of high-intensity interval training (HIIT) and moderate-intensity continuous training on serum BDNF and other outcomes in stroke patients." (PMID 33671531, 2021). "Regarding the role of BDNF as an acute stroke biomarker, the data available are insufficient, and further research is needed." (PMID 33809965, 2021). "Recently published studies presented the crucial role of BDNF in ischemia, suggesting its correlation with post-stroke mobility." (PMID 32944919, 2021). "In contrast, Rhy appears to restore BDNF level when it is decreased in pathological conditions instead of increased, such as in the cortex or hippocampus of a rat stroke model or of chronic/social-defeat stressed mice." (PMID 34207633, 2021). "It was reported that AT enhances brain plasticity following a stroke in mice via increasing the mRNA expression of BDNF." (PMID 35096297, 2021). "In humans after stroke, Cytoflavin showed increased levels of BDNF, and improved cognitive functions after recovery." (PMID 34693660, 2021). "Neurotrophins such as brain-derived neurotrophic factor (BDNF) mediate protection and recovery following stroke." (PMID 34108925, 2021). "Recently, it has been shown that the transcription factor CREB, which induces BDNF, promotes recovery after stroke." (PMID 32378029, 2021). "We also proved that BDNF levels in patients with stroke are significantly increased compared to healthy controls." (PMID 33809965, 2021). "In the acute stroke phase, BDNF levels in serum were negatively correlated with NIHSS, which reached statistical significance (random-effects model COR: −0.3013, 95%CI: (−0.4725; −0.1082), z = −3.01, p = 0.0026)." (PMID 33809965, 2021). "An increase in BDNF was sufficient to preserve synaptic vesicle proteins and facilitate behavioral recovery in post-stroke mice, partially via MAPK signaling." (PMID 33631722, 2021). "Both functional outcome and BDNF levels were measured at admission, day 7, 3 months, and 12 months after stroke." (PMID 33809965, 2021). "In another study, an infusion of BDNF in combination with vascular endothelial growth factor (VEGF) increased SVZ neurogenesis in mice after stroke." (PMID 34768919, 2021). "In animal models of stroke, local application of BDNF has been shown to improve recovery of neuronal function after ischemic injury." (PMID 34557534, 2021). "The endpoints examined were the correlation of BDNF with functional outcome, the National Institute of Health stroke scale (NIHSS) measured at the acute phase, and stroke infarct volume." (PMID 33809965, 2021). "We also have shown that BDNF expression is a major contributor to the positive effects of RAS modulation in experimental stroke." (PMID 33572986, 2021). "Previously, researchers had used hyaluronic acid hydrogel loaded with BDNF for nerve repair in patients at the chronic phase after stroke, and found that BDNF can be released locally from the infarct cavity." (PMID 35194435, 2021). "We previously identified two elevated markers of cerebral injury, plasma brain-derived neurotropic factor (BDNF) and platelet-derived growth factor (PDGF)-AA, in children with SCA and high stroke risk." (PMID 35935682, 2021).